NTHL1 (nth like DNA glycosylase 1)
Diseases named in the same sentence as NTHL1 in open-access papers (continued):
Sharing a sentence is not in itself a finding about the gene and the disease.
tumor (34 papers, 2013 to 2025). "NTHL1-deficient tumours harbour the highly specific signature SBS30, associated with an enrichment of C>T nucleotide transitions." (PMID 40237887, 2025). "They further showed that SBS30 was the main mutational process in these tumours, highlighting that different tissue sources can be used to determine biallelic NTHL1-deficiency." (PMID 39793275, 2025). "We also showed loss of the wild-type allele in the tumour DNA from the left and the right ovaries from two NTHL1 c.244C>T carriers with bilateral OC." (PMID 36969007, 2023). "Carriers of biallelic nonsense mutations in the NTHL1 gene can develop both intestinal symptoms, but also multi tumor phenotype." (PMID 36553592, 2022). "One of two cases that harbored germline inactivating NTHL1 variant (p.Gln90*) had evidence of tumor variant enrichment." (PMID 33917078, 2021). "The broad increase in tumor incidence in those patients harboring the NTHL1 nonsense mutation established a novel “NTHL1 syndrome”." (PMID 32595826, 2020). "Moreover, we observed partial or complete loss of the wild-type alleles in the tumour DNA from the left and the right ovaries from both NTHL1 variant carriers having bilateral OC." (PMID 36969007, 2023). "Because NTHL1 deficiency may also predispose to extracolonic tumors, the risk for these tumor types in monoallelic NTHL1 carriers still needs further assessment." (PMID 32860789, 2020). "A review of previously reported obligate heterozygous carriers of NTHL1 variants showed two patients affected with neoplasms at <55 years of age, generating a study to outline the phenotypic spectrum in patients with heterozygous pathogenic NTHL1 variants relevant." (PMID 31645984, 2019). "For the heterozygous germline variants in other DNA damage repair genes, MUTYH and NTHL1, the mutational signature analysis indicates possible involvement in the etiology of EC, but only when there were indications of the germline variant being enriched in the tumor." (PMID 33917078, 2021). "This case suggests that heterozygous NTHL1 variants may be implicated in tumor development." (PMID 34367820, 2021). "However, reported manifestations found in obligate NTHL1 heterozygous carriers in the literature may suggest a heightened risk of developing other neoplasms." (PMID 31645984, 2019). "We showed loss of the wild-type allele in tumours from carriers of ERCC5 c.2556A>G, NEIL1 c.248G>T; p.Gly83Asp or NTHL1 c.244C>T; p.Gln82Ter." (PMID 36969007, 2023). "Only 1 tumor showed a minor SBS30 contribution to the mutation profile, but this contribution was far less significant compared to NTHL1-deficient CRC and is likely the result of multiple testing correction." (PMID 32860789, 2020). "Tumour DNA from ERCC5, NEIL1 and NTHL1 variant carriers exhibited loss of the wild-type allele." (PMID 36969007, 2023). "Nevertheless, due to its multi-tumor broad spectrum phenotype, some NTHL1 families can resemble other hereditary syndromes and may mislead genetic counseling, especially if the clinical information is incomplete." (PMID 37727376, 2023). "In our patient #1, the variant in NTHL1 was apparently mosaic in normal tissue and disappeared in the tumor DNA, without any evidence of a second mutational event in NTHL1." (PMID 38002998, 2023). "Person 4, the father of patients 1 and 2, is also an obligate heterozygous carrier of the NTHL1 variant and has no neoplasms or thyroid-associated diseases." (PMID 31645984, 2019). "One study reported that other tumor suppressors resulting in MSS tumors, such as MutYH, PolD, PolE, and NTHL1, might be associated with the pathogenesis of CRC in addition to APC gene mutations." (PMID 29237421, 2017). "Consistent with the bioinformatic prediction, GTF3C1, NR1H3, NTHL1, SNX, TMEM132A and WIZ expressions were markedly upregulated in the tumor group relative to the normal group." (PMID 41573564, 2025).
tumor (continued). "Unique molecular characteristics have been described in neoplasms from defective DNA repair-related polyposis involving the MUTYH, NTHL1, MBD4, MSH3, POLE and POLD1 genes and the MMR genes in CMMRD." (PMID 40237887, 2025). "The expression levels of three writers (DNMT1, DNMT3A, DNMT3B), two erasers (TET1, TET3), and eight readers (MBD4, ZBTB33, UHRF1, UHRF2, UNG, TDG, NTHL1, SMUG1) were dramatically higher in tumor tissues (p < 0.05)." (PMID 38317133, 2024). "Additionally, VUS (CDON and NTHL1) were identified in 2 patients for whom tumor DNA was not available." (PMID 38655100, 2024). "However, we observed no LOH in tumour DNA from one carrier each of ERCC5 or NEIL1 variants and two carriers of NTHL1 variant." (PMID 36969007, 2023). "Biallelic LoF variants in the NTHL1 gene have been shown to drive a mutational process causing the COSMIC signature SBS30, which is characterized by somatic C>T transitions at non-CpG sites over different tumour types, including BC6,9,12,25,31,32." (PMID 38036545, 2023). "Therefore, characterization of NTHL1 as a tumor suppressor does not depend only on the catalytic functions (glycosylase/lyase activities) but also on the functions of the N-terminal disordered region." (PMID 32595826, 2020).
benign tumors (3 papers, 2021 to 2023). "Heterozygous mutations in NTHL1 can usually cause benign tumors." (PMID 36979978, 2023). "We previously published a case of benign tumors associated with a heterozygous NTHL1 mutation." (PMID 35967160, 2022).
infection (2 papers, 2017 to 2020). The state of being infected such as from the introduction of a foreign agent such as serum, vaccine, antigenic substance or organism. "The protein levels of NTHL1, MUTYH, FEN1, RAD51, POLD1, and LIG1 were observed to be decreased, during the infection, in a CagA- and phospho-CagA-related manner in both cell lines." (PMID 33339161, 2020).
NTHL1 also shares sentences with these, for which no sentence is quoted: pancreatic cancer (4 papers); juvenile polyposis syndrome (3); Cowden disease (2); cyst (2); hepatocellular carcinoma (2); hereditary mixed polyposis syndrome (2); meningioma (2); pancreatic NET (2); Parkinson disease (2); adenocarcinoma (1); allergic asthma (1); Alzheimer disease (1); autosomal recessive inherited disorder (1); basal cell carcinoma (1); cervical carcinoma (1); CMMRD syndrome (1); gastric cancer (1); head and neck cancer (1); head and neck squamous cell carcinoma (1); hereditary cancer syndrome (1); hereditary colorectal cancer (1); hyperplastic polyp (1); immunodeficiency disorder (1); juvenile polyp (1); laryngeal carcinoma (1); liver cancer (1); lung carcinoma (1); lung squamous cell carcinoma (1); Lynch syndrome (1); multiple sclerosis (1).
A further 12 diseases each share a sentence with NTHL1 in 1 paper.